IL33 (interleukin 33)
Diseases named in the same sentence as IL33 in open-access papers (continued):
Sharing a sentence is not in itself a finding about the gene and the disease.
type 1 diabetes (8 papers, 2012 to 2025). "To investigate the pathophysiological relevance of IL-33 in vivo, we examined its activity in 2 distinct animal models that mechanistically represent type 1 diabetes and T2D, respectively: high-fat diet Streptozotocin and db/db uninephrectomized (unx)." (PMID 38899206, 2024). "Here, we found that short‐term IL‐33 treatment significantly prolonged islet allograft survival in STZ‐induced type 1 diabetic mice." (PMID 33034128, 2020). "Present study was undertaken to analyze the effect of exogenous IL-33 on the onset and the development of type 1 diabetes as evaluated by glycemia, glucose tolerance test, glycosuria, and islet infiltration." (PMID 30498495, 2018). "In this paper we add the evidence that not only genetic deletion of IL-33 receptor (ST2) enhance T cell mediated autoimmune inflammatory diseases but also the exogenous IL-33 has shown powerful preventive effect in a model of type 1 diabetes." (PMID 30498495, 2018). "In a group of patients with type 1 diabetes in vitro IL-33 treatment induced regulatory CD4+CD25highFOXP3+ cells." (PMID 27761063, 2016). "As type 1 diabetes is an autoimmune, inflammatory disease, where Treg defects have been described, we aimed to analyze the in vitro influence of recombinant IL-33 on quantitative properties of regulatory CD4+CD25highFOXP3+ T cells." (PMID 27761063, 2016). "We propose that IL-33 becomes an additional immunostimulatory factor used to induce Treg expansion in future clinical trials of adoptive therapy in type 1 diabetes." (PMID 27761063, 2016). "Taking into account these facts, the aim of the current study was to analyze the in vitro effect of IL-33 on the quantitative properties of regulatory CD4+CD25highFOXP3+ T cell population in patients with type 1 diabetes." (PMID 27761063, 2016). "In a group of patients with type 1 diabetes in vitro IL-33 treatment induced regulatory CD4+CD25highFOXP3+ cell frequencies as well as upregulating the surface expression of ST2 molecule." (PMID 27761063, 2016). "It was upregulated on cells from patients with type 1 diabetes cultured in medium containing IL-33." (PMID 27761063, 2016). "IL-33 could induce Treg cells in patients with type 1 diabetes; however, more studies including qualitative characterization of IL-33 treated CD4+CD25highFOXP3+ on a larger group of patients need to be done." (PMID 27761063, 2016). "Furthermore, IL-33 signaling through ST2L is proposed to limit destructive Th17 responses in a murine model of type 1 diabetes." (PMID 23112853, 2012). "Finally, it was recently suggested to use IL-33 to potentiate highly suppressive TREG cells ex vivo, as adoptive transfer of these cells attenuates disease progression in a model of type 1 diabetes." (PMID 30949175, 2019). "To date, there are no data on the influence of IL-33 on FOXP3+ regulatory T cells in patients with type 1 diabetes." (PMID 27761063, 2016).
urticaria (8 papers, 2017 to 2024). A vascular reaction of the skin characterized by erythema and wheal formation due to localized increase of vascular permeability. "Proinflammatory cytokines, particularly IL-33, promote the adhesion, maturation, and degranulation of mast cells in urticaria." (PMID 38989334, 2024). "The cytokines promoting a Th2 profile, such as IL-33 and IL-25 in association with vasoactive agents (e.g., VEGF), are identified in urticaria lesions, but not in healthy skin." (PMID 38541037, 2024).
acute coronary syndrome (7 papers, 2014 to 2024). Signs and symptoms related to acute ischemia of the myocardium secondary to coronary artery disease. "A subsequent study stressed the prognostic significance of IL-33 in patients after revascularized acute coronary syndrome, with higher levels indicating a higher disease complexity and poorer 1-year prognosis." (PMID 36555579, 2022). "Accordingly, patients with ISR showed a significant increase of IL-33 upon PCI (p < 0.05) in the entire cohort as well as in the patients with acute coronary syndrome (ACS) or stable CAD." (PMID 24725541, 2014). "However, a study of IL-33 levels in patients with acute coronary syndrome (ACS) showed that IL-33 levels gradually decreased after ACS in patients with ST-segment elevation myocardial infarction (STEMI), in contrast with sST2, which has constant levels over the same period." (PMID 39194749, 2024). "Moreover, IL-33 emerged as an independent predictor of acute coronary syndrome incidence." (PMID 36555579, 2022). "Although increased levels of sST2 in patients with STEMI and NSTEMI were shown over different periods of time, a comparison of sST2 and IL-33 concentrations in patients with stable angina and acute coronary syndromes and individuals without CAD was not studied before and was the aim of our study." (PMID 24751794, 2014).
allergic respiratory disease (7 papers, 2012 to 2025). A respiratory system disease with a basis in a pathological type I hypersensitivity reaction. "Basal-cell hyperplasia, which is commonly associated with allergic respiratory disease, is correlated with the basal-cell production of alarmins such as IL-33 and TSLP, as well as with IL-4/IL-13-induced gene signaling in basal cells." (PMID 39653767, 2025). "Our findings were supported by some other studies showing that BaP can directly induce AhR activation that contributes to the pro-inflammatory response in respiratory allergy through enhancing IL-33 expression and eosinophil infiltration." (PMID 33936062, 2021). "Using a model of respiratory dysbacteriosis in mice, it was found that respiratory tract microbiome imbalance improved the progress of allergic respiratory diseases, and this was by promoting the local production of IL-33." (PMID 34054744, 2021). "Accordingly, recombinant sST2 antagonizes the pro-inflammatory effect of IL-33 in respiratory allergy." (PMID 32069819, 2020).
amyotrophic lateral sclerosis (7 papers, 2015 to 2025). Amyotrophic lateral sclerosis (ALS) is a neurodegenerative disease characterized by progressive muscular paralysis reflecting degeneration of motor neurons in the primary motor cortex, corticospinal tracts, brainstem and spinal cord. "Prolonged IL-33 administration delays the onset of the disease in transgenic mice afflicted with amyotrophic lateral sclerosis and attenuates astrocyte activation." (PMID 40764944, 2025). "Interleukin-33 (IL-33) levels were found to be lower in many neurodegenerative diseases such as Alzheimer’s and amyotrophic lateral sclerosis (ALS)." (PMID 38694387, 2024). "IL-33 levels in serum is lower in patients with amyotrophic lateral sclerosis (ALS) than those in healthy controls." (PMID 34079543, 2021). "Furthermore, IL-33 levels were found to be lower in many neurodegenerative diseases such as Alzheimer’s and amyotrophic lateral sclerosis (ALS)." (PMID 38694387, 2024). "Low levels of IL-33 and high levels of sST2 were noted in patients with HIV infection or amyotrophic lateral sclerosis." (PMID 25802482, 2015). "Another explanation for lack of increase in IL-33 levels in active AAV might be that IL-33 is subject to degradation by caspases released from the apoptotic cells in AAV, in accordance with the hypothesis that was suggested for amyotrophic lateral sclerosis." (PMID 25802482, 2015).
anemia (7 papers, 2019 to 2023). A reduction in the number of red blood cells, the amount of hemoglobin, and/or the volume of packed red blood cells. "Erythroid progenitors preferentially express ST2, the receptor for IL-33; this cytokine is necessary and sufficient to cause anemia during chronic inflammation." (PMID 32520308, 2020). "Conversely, administration of IL-33 in healthy mice suppressed erythropoiesis, decreased hemoglobin expression, and caused anemia." (PMID 32520308, 2020). "The most often cause for development of microcytic anemia is iron deficiency, while on the other hand iron sequestration facilitated by IL-1 and IL-33 might be an alternative cause of anemia in CRC patients." (PMID 35611243, 2022). "IL-33 has been proposed as a novel contributor to anemia in inflammatory disease through its effects on differentiation of erythroid cells and as a therapeutic target for this type of patients." (PMID 36969226, 2023). "We have analyzed the Receiver Operating Characteristic (ROC) curves of serum IL-33, Gal-1 and IL-1 showed that these cytokines can be treated as additional markers for anemia of inflammation in CRC patients." (PMID 35611243, 2022). "Predomination of Galectin-1, IL-1 and IL-33 in anemic CRC patients implicates on their potential role in anemia genesis and further development." (PMID 35611243, 2022). "Presented data revealed higher Galectin-1, IL-1 and IL-33 values in serum of CRC patients with anemia, establishing them as new players in genesis and progression of anemia of inflammation." (PMID 35611243, 2022). "The other study showed that mice with over expression of IL-33 had detectable anemia and thrombocytosis." (PMID 35611243, 2022). "The optimal cut off levels of cytokines estimated for confirmation of anemia in CRC patients was 31.58 pg in mL (IL-33), 7257.07 pg in mL (Gal-1), 8.9624 pg in mL (IL-1)." (PMID 35611243, 2022). "IL-33 is an epithelial cytokine involved in both physiological and immune responses in mucosal tissues, where it promotes anemia during chronic inflammation by decreasing hemoglobin expression and inhibiting the differentiation of erythroid progenitors during erythropoiesis." (PMID 36831233, 2023). "Furthermore, IL-33 promotes anemia during chronic inflammation by inhibiting the differentiation of erythroid progenitors." (PMID 37630681, 2023). "Further, examination of ROC curves of Gal-1, IL-33 and IL-1 revealed that these cytokines could predict anemia of inflammation in CRC patients." (PMID 35611243, 2022). "Examination of ROC curves of IL-33, Gal-1 and IL-1 values in serum showed that these cytokines could predict anemia in CRC patients." (PMID 35611243, 2022). "Our result revealed significantly higher systemic IL-33 concentration in anemic CRC patients, positive association between CA 19-9 and IL-33 and negative association between hemoglobin and IL-33, suggesting on possible role of this proinflammatory cytokine in pathogenesis of anemia in CRC patients." (PMID 35611243, 2022). "IL-10 but not IL-33 has been linked to lower ferritin levels and anemia." (PMID 31333751, 2019). "Significantly higher concentrationof IL-33 (p = 0.003), Gal-1 (p = 0.009) and IL-1 (p= 0.005) have been found in serum of CRC patientswith detected anemia." (PMID 35611243, 2022). "Significantly higher IL-33, Gal-1 and IL-1 concentration have been found in sera of patients with CRC and detected anemia." (PMID 35611243, 2022). "Revelation of positive correlation between systemic IL-1, IL-33 and galectin-1 levels in serum of anemic CRC patients suggested on synergistic effect of these cytokines in pathogenesis of anemia in CRC patients." (PMID 35611243, 2022). "Concentrations of IL-33, Galectin-1 and IL-1 have been studied in blood samples of 55 CRC patients (27 without anemia and 28 with anemia)." (PMID 35611243, 2022).
anemia (continued). "CRC patients with microcytic anemia (MCV < 83fL) had significantly higher IL-33 (p = 0.009), Gal-1 (p = 0.002) and IL-1 (p = 0.013) in sera in comparison to CRC patients with normocytic anemia or without anemia." (PMID 35611243, 2022).
autoimmune uveitis (7 papers, 2014 to 2025). An autoimmune form of uveitis (disease). "Previous studies have shown that IL-33-induced M2 macrophage polarization reduces retinal inflammation and even ameliorates experimental autoimmune uveitis, underscoring its potential as a therapeutic target in ocular inflammatory diseases." (PMID 40512033, 2025). "IL-33 was constitutively expressed in the inner nuclear cells of normal retina and was greatly upregulated in autoimmune uveitis mice." (PMID 32908451, 2020). "In an experimental autoimmune uveitis mouse model, IL-33 slows down disease progression with decreased retinal inflammation." (PMID 31450606, 2019). "Here, we investigated the function of IL-33 in the development of experimental autoimmune uveitis (EAU)." (PMID 25116404, 2014). "Recent papers reported that IL-33 attenuates EAE and experimental autoimmune uveitis by suppressing IL-17A and IFN-γ production." (PMID 26161006, 2015). "However, the precise role of the IL-33/IL-31 axis in equine recurrent uveitis (ERU) and autoimmune uveitis remains unclear and warrants further investigation." (PMID 39519064, 2024). "Previous studies have reported that IL-33 can function as both a proinflammatory and an inflammatory cytokine during the immune response, as anti-apoptotic and survival molecules can protect from oxidative stress by increasing SOD activity and can attenuate the development of autoimmune uveitis." (PMID 31450606, 2019).
Behçet’s disease (7 papers, 2019 to 2024). "IL-33 also played a role in other rheumatic diseases such as idiopathic inflammatory myopathies (IIM), adult-onset Still's disease (AOSD), and Behcet's disease (BD)." (PMID 34589505, 2021). "It is also noteworthy that levels of IL-33 and soluble ST2 were elevated in serum of patients with the autoinflammatory Behcet's disease." (PMID 31416928, 2019).
chronic hepatitis (7 papers, 2012 to 2025). An active inflammatory process affecting the liver for more than six months. "Our research demonstrates that blocking the IL-33/Treg signaling axis, particularly through statin treatment, can effectively suppress chronic hepatitis and prevent HCC development in HBV-infected individuals." (PMID 40579434, 2025). "By targeting the IL-33/Treg axis with pitavastatin, we offer a promising approach for the prevention and treatment of chronic hepatitis and its cancer sequelae in HBV-infected individuals." (PMID 40579434, 2025). "Pro-inflammatory responses triggered by IL-33 have been suggested in the pathogenesis of acute and chronic hepatitis and their sequelae." (PMID 32486265, 2020). "In humans suffering from chronic hepatitis, there also exists at the level of the liver a correlation between IL-33 cellular expression and fibrosis severity." (PMID 31507607, 2019). "Furthermore, suppressing IL-33/Treg axis in the liver using statins represents a safe and effective strategy for the prevention and treatment of chronic hepatitis and its cancer sequelae." (PMID 40579434, 2025). "IL-33 has been shown to be upregulated in human and murine acute and chronic hepatitis." (PMID 28607531, 2017). "Recent reports hypothesized IL-33 to be involved in the pathogenesis of liver damage during acute and chronic hepatitis." (PMID 23423835, 2012).
chronic hepatitis B (7 papers, 2015 to 2023). "The elevation of IL-33 has been observed in a number of types of cancers, in COVID-19 infection and in chronic hepatitis B infection." (PMID 38035159, 2023). "Serum levels of IL-33 and soluble ST2 vary in different courses of chronic hepatitis B virus infection, and the serum levels of IL-33 and soluble ST2 elevate as serum ALT levels increased in patients with CHB." (PMID 32410845, 2020). "The elevation of IL-33 has been observed in a number of types of cancers and other chronic viral infection, such as chronic hepatitis B infection." (PMID 30564243, 2018). "We therefore sought to investigate the serum measurements of IL-33 and ST2 in patients with chronic hepatitis B virus infection and study the relationship of IL-33 and ST2 with ALT and HBeAg." (PMID 27180842, 2016). "Other studies found that IL-33 was upregulated in T2DM patients with chronic hepatitis B." (PMID 37238986, 2023). "Our study revealed that the serum levels of IL-33 and ST2 varied in different courses of chronic hepatitis B virus infection." (PMID 27180842, 2016). "The serum levels of IL-33 and ST2 varied in different courses of chronic hepatitis B virus infection." (PMID 27180842, 2016). "We surmised that IL-33 and ST2 might indicate liver damage of patients with chronic hepatitis B, just like ALT." (PMID 27180842, 2016). "We found that plasma levels of sST2 but not IL-33 were higher in HBV-ACLF patients compared with chronic hepatitis B (CHB) patients and healthy controls." (PMID 25892854, 2015).
chronic myelogenous leukemia (7 papers, 2018 to 2025). "In the context of AML as well as chronic myeloid leukemia, the IL-33/IL1RL1 axis has been involved in only two reports." (PMID 40659660, 2025). "Herein, the authors show in an inducible murine model of chronic myelogenous leukaemia that a systemic inflammatory state can trigger IL-33- mediated IL-9 production that leads to small intestinal remodelling and PCM." (PMID 38042840, 2023). "Further studies showed that in basophil-like chronic myelogenous leukemia KU812 cells, the ST2 receptor is constitutively expressed and facilitates the production of cytokines, chemokines, and growth factors in response to IL-33." (PMID 30205617, 2018).
co-infection (7 papers, 2017 to 2023). "Our data showed a positive association between plasma IL-33 and viral load in the context of HIV/TB coinfection in our study population with a positive Pearson coefficient of r=0.21." (PMID 38035159, 2023). "The increased levels of plasma IL-33 indicate that IL-33 measurement in HIV-1 monoinfected patients can be a potential surrogate marker of immune activation in the context of HIV-TB coinfection in a resource-limited setting." (PMID 38035159, 2023). "In this study, we additionally report the regulation of proinflammatory (IL1-α, IL1-β, IL6, IL8, IL18, and TNF-α) and regulatory (IL10, IL22, IL23, and IL33) cytokines associated with single-PDCoV and -PEDV infection, as well as PDCoV/PEDV co-infection." (PMID 36376395, 2022). "To identify if IL-33 contributed to raised pathology in co-infection, we treated Nb + HSV-2 mice intravaginally with the IL-33 inhibitor heligmosomoides polygyrus alarmin release inhibitor (HpARI)." (PMID 33857419, 2021). "This body of work supports vaginal epithelial cells to be the key source of IL-33-mediated type 2 immunity in the FGT during co-infection." (PMID 33857419, 2021). "This was convincingly substantiated by the observation that plasma IL-33 levels increased with viral load in HIV/TB coinfected individuals clearly establishing the positive association between plasma IL-33 and viral load in the context of HIV/TB coinfection in our study population (r=0.21, p=0.34)." (PMID 38035159, 2023). "Moreover, our findings support a pro-inflammatory role for IL-33 in the presented co-infection scenario." (PMID 33857419, 2021). "Co-infection of helminth species is quite common in Brazil, particularly between hookworm (N. americanus) and Schistosoma mansoni, but the effects of these infections on TFFs or IL-33, either alone or together is unknown." (PMID 34662329, 2021). "This study evaluated the regulatory effect of single- and PDCoV/PEDV co-infection on regulatory cytokines (IL10, IL22, IL23, and IL33)." (PMID 36376395, 2022). "In this way, HIV-induced production of IL-33, protective for HIV-1 patients under highly active antiretroviral therapy, appeared to be detrimental for naïve HIV-1/TB coinfected patients, contributing to HIV-1 persistence and tissue damage in the context of HIV/TB coinfection." (PMID 38035159, 2023). "Therefore, we sought to determine what effect co-infection of hookworm and Schistosoma, or either infection alone might have on TFF2, TFF3, and IL-33 levels in serum as compared to both endemic and non-endemic controls, accounting for age and sex as covariates." (PMID 34662329, 2021).